NAT8B (N-acetyltransferase 8B (putative, gene/pseudogene))
Description:
Endoplasmic reticulum (ER)-membrane-bound lysine N-acetyltransferase catalyzing the N6-acetylation of lysine residues in the lumen of the ER in various proteins, including PROM1 and BACE1, using acetyl-CoA as acetyl donor. Thereby, may regulate apoptosis through the acetylation and the regulation of the expression of PROM1. Acetylates and stabilizes BACE1 immature protein, leading to increased steady-state levels in neurons. By acting on BACE1 expression, may regulate amyloid beta-peptide formation. N(6)-lysine acetylation in ER maintains protein homeostasis and regulates reticulophagy (By similarity).
Synonyms: CML2; Hcml2; NAT8BP
Gene: Unitary pseudogene on chromosome 2 (73,700,622 to 73,701,305, reverse strand). Ensembl gene ENSG00000204872.
Subcellular location: Endoplasmic reticulum-Golgi intermediate compartment membrane; Endoplasmic reticulum membrane
Subcellular location (Human Protein Atlas): Endoplasmic reticulum
Genetic constraint (gnomAD): Missense variants: 372 observed, 296.57 expected, observed/expected ratio (o/e) 1.25, 90% interval 1.15 to 1.37. Synonymous variants: 150 observed, 124.03 expected, observed/expected ratio (o/e) 1.21, 90% interval 1.06 to 1.38.
Diseases named in the same sentence as NAT8B in open-access papers:
NAT8B is named in the same sentence as 11 diseases in open-access papers, as found by Europe PMC text mining. Sharing a sentence is not in itself a finding about the gene and the disease. The quoted sentences say what the papers report.
progeria (3 papers, 2022 to 2025). "Gene duplication events involving 3q25.31 (harboring AT-1/SLC33A1) and 2p13.1 (harboring ATase1/NAT8B and ATase2/NAT8) are associated with autism spectrum disorder with intellectual disability and progeria-like dysmorphism." (PMID 40930841, 2025).
NAT8B also shares sentences with these, for which no sentence is quoted: Alzheimer disease (2 papers); Intellectual disability (2); proteopathy (2); asthma (1); autism (1); autism spectrum disorder (1); chronic kidney disease (1); colorectal adenocarcinoma (1); Rectal prolapse (1); sarcopenia (1).